BMPR1A (bone morphogenetic protein receptor type 1A)
Diseases named in the same sentence as BMPR1A in open-access papers (continued):
Sharing a sentence is not in itself a finding about the gene and the disease.
breast carcinoma (24 papers, 2010 to 2025). "We found that loss of BMPR1a resulted in mammary tumors with EMT-like changes, but with delayed growth and progression." (PMID 26274893, 2015). "ACVR1 and BMPR1A have each been previously associated with breast cancer." (PMID 30566622, 2019). "Finally, among the breast cancer predisposition genes with moderate/high-penetrance, seven genes (BMPR1A, PTEN, CDH1, NF1, RAD51C, BRIP1, and CHEK2) were replicated for Korean BRCAX (eight for Asian and 15 genes for European high-risk breast cancers)." (PMID 30323354, 2018). "CTL and BMPR1a-cKO mice were i.p. injected with β-glucan 7 days prior to intratibial injection of the syngeneic MMTV-PyMT mammary carcinoma bone clone to seed bone metastases." (PMID 38193534, 2024). "Supporting this discovery, there was also study reporting that the O-GalNAcylation of BMPR1A by GALNT8 enhanced its activity to transduce BMP signaling in breast cancer." (PMID 38385080, 2024). "Another study indicated that the silencing of BMPR1A suppressed osteoclastogenesis in breast cancer cells by inhibiting RANKL via p38 pathway." (PMID 38783645, 2024). "Knockout of BMPR1A in a mouse model of mammary tumors delayed tumor initiation and prolonged survival in human breast cancer." (PMID 37373155, 2023). "The BMPR1A nonsynonymous SNV (rs55932635) was identified in one of 56 BRCA-negative breast cancer patients in Puerto Rico, while the JAK2 nonsynonymous SNV (rs200018153) was found in one of 1487 acute myeloid leukaemia (AML) patients in the United States." (PMID 35954343, 2022). "BMPR1a has recently been identified in breast cancer as responsible for switching osteolytic breast cells into a blastic state." (PMID 34956082, 2021). "The second case was a 38 year-old breast cancer female who presented the c.1166G > T, p.(Ser389Ile) in the BMPR1A gene." (PMID 31159747, 2019). "We have conditionally deleted BMPR1a in a breast cancer mouse model (Polyoma middle T–PyMT) to determine tumor suppressive or promoting functions." (PMID 26274893, 2015). "We had also reported that high BMPR1a expression was the only type I TGFβ receptor to correlate with poor relapse free survival (RFS) in human breast cancers." (PMID 26274893, 2015). "Our data suggest that BMPR1a has a function unrelated to breast cancer molecular subtypes, which suggests that targeting BMPR1a is a potential therapy for all subtypes of breast cancer." (PMID 26274893, 2015). "In contrast, in breast cancer BMPR1A activity was shown to promote cell proliferation via SMADs, whereas results for BMPR2 are contradictory." (PMID 22277058, 2012). "Similarly, it was reported that the inhibition of BMPR1A alleviated the formation and metastasis of breast cancer." (PMID 38783645, 2024). "Low expression of BMPR1A also blocks the progression and metastasis of breast cancer, and BMPR1A may play a role in promoting the metastasis of GTN." (PMID 31998776, 2020). "Established markers for breast cancer cells (BRCA1, MAP3K1, BMPR1A) and fibroblasts (FN1, VIM, COL6A2) were used to classify the clusters." (PMID 39805002, 2025). "LysMCre control (CTL) and LysMCre myeloid cell–restricted BMPR1a–conditional KO (BMPR1a-cKO) mice were used to examine whether myeloid cell BMP signaling was necessary or sufficient alongside β-glucan trained immunity stimulus to alter mammary carcinoma bone metastasis progression." (PMID 38193534, 2024). "BMP2, BMP4, GDF11 and TGFBR2 had relatively higher levels in bone metastases of breast cancer while BMP5, BMP7, BMPR2, BMPR1A and ACVR2A presented lower expression in the bone metastases, in the E-MTAB-4003 dataset." (PMID 37333824, 2023). "Genetic alterations in BMPR1A, BMPR1B, or BMPR2 were found in around 6, 7, or 5% of patients with breast cancer, respectively, with the major form of genetic alternation being an upregulation of mRNA encoding BMP receptors (data not shown)." (PMID 31409851, 2019).
breast carcinoma (continued). "When queried for the three most common BMP receptors: BMPR1a, BMPR2 and BMPR1b, BMPR1a and BMPR2 are largely equally distributed for high and low expression between the four largest molecular subtypes of breast cancer." (PMID 26274893, 2015). "We have previously reported that all six BMP specific receptors (ACVR1, BMPR1A, BMPR1B, ACVR2A, ACVR2B, and BMPR2) are uniformly expressed among the breast cancer cell lines studied here." (PMID 22118688, 2011). "Correlation between BMPR1A and EMT markers was evident in HER2 positive and TNBC breast cancers." (PMID 37333824, 2023). "That study also analysed human data sets and found a correlation between high BMPR1A gene expression and decreased survival, regardless of the molecular breast cancer subtype, and concluded that BMPR1A is a tumour promoter in human breast cancer." (PMID 32714600, 2020).
colorectal cancer (18 papers, 2009 to 2025). A primary or metastatic malignant neoplasm that affects the colon or rectum. "To exclude other possible predisposing variants beyond BMPR1A, we conducted exome sequencing on 2–3 members with colorectal cancer and/or polyps from each family." (PMID 41023686, 2025). "Those with DCVs in BMPR1a who present at a young age (under 10 years), with high numbers of colorectal polyps (> 50) or who develop colorectal cancer are presumed to carry a DCV which causes a more penetrant phenotype of JPS." (PMID 37400896, 2023). "Patients with BMPR1a DCVs who developed colorectal cancer only possessed DCVs in the coding regions of the gene, including one patient with a whole gene deletion of BMPR1a.." (PMID 37400896, 2023). "Colorectal cancer occurs at a similar incidence in both causative genes of JPS, where 15/127 (11.8%) had CRC in SMAD4 carriers, compared to 7/94 (7.4%) in BMPR1A carriers." (PMID 38066625, 2023). "Inactivation of BMPR1A, BMPR2, and SMAD4 was frequently observed in sporadic colorectal cancer, correlating to loss of Smad1/5/8 phosphorylation." (PMID 22072987, 2011). "About 5% of colorectal cancer cases are associated with germline mutations of genes such as APC, DNA mismatch repair genes, MYH, SMAD4 and BMPR1A/ALK3." (PMID 19538729, 2009). "Experimental approaches such as CRISPR-based knockout or knock-in of SMAD4 and BMPR1A in colorectal cancer cell lines and patient-derived organoids could directly test their effects on chemoresistance and tumor progression." (PMID 41009631, 2025). "We, here, scrutinized four families segregating non-truncating BMPR1A variants and having clinical presentation of familial non-polypotic colorectal cancer or FCCTX." (PMID 41023686, 2025). "We conducted a clinical and molecular investigation on four families clinically presenting as familial colorectal cancer with MMR-proficient tumors and diagnosed with heterozygous non-truncating BMPR1A variants by targeted sequencing." (PMID 41023686, 2025). "In summary, DCVs causing diagnosis at a young age, high colorectal polyp numbers or colorectal cancer are seen across all functional domains of the gene, and include all DCV types, suggesting a BMPR1a genotype–phenotype correlation cannot be identified from the given DCVs in BMPR1a." (PMID 37400896, 2023). "Biologically, the results reinforce the dual role of TGF-β signaling in colorectal cancer: functioning as a tumor suppressor in early stages, but shifting toward pro-metastatic, immune-evasive, and chemoresistant roles when disrupted through alterations in key regulators such as SMAD4 and BMPR1A." (PMID 41009631, 2025).
polyposis (13 papers, 2013 to 2023). "Loss of BMPR1A in mesenchymal cells results in reactive stroma and subsequent polyposis, supporting the idea that BMP signaling loss in the stroma is sufficient to initiate polyp development." (PMID 36326956, 2023). "There appears to be some phenotypic overlap between the autosomal dominant nonsense variants that cause polyposis and complete deletions of BMPR1A who also have polyposis." (PMID 31493347, 2019). "In general, we observed that the clinical spectrum of patients with a PV in SMAD4 or BMPR1A was very wide: from massive polyposis (both gastric and colorectal) to very few colorectal polyps." (PMID 37354305, 2023). "All these facts make the p.Q82* of the NTHL1 gene screening reasonable in polyposis patients (especially in an unusual disease course), with APC, MUTYH, STK11, BMPR1A, and SMAD4 mutations excluded." (PMID 37834005, 2023). "Deletion of Bmpr1a with Dmp1-Cre results in polyposis throughout the stomach and intestines, demonstrating a critical role of mesenchymal BMP signaling in maintaining a normal gastrointestinal tract." (PMID 28163952, 2017). "Similarly, simultaneous deletion of Bmpr1a in the stromal and epithelial compartments yields hyperproliferative crypts that eventually lead to polyposis." (PMID 33673710, 2021). "Besides JPS and GI cancers, BMPR1A is also associated with HMPS, polyposis, superior coloboma, and CHD, while SMAD4 is also associated with HHT, Myhre syndrome, Loeys-Dietz syndrome, cholangiocarcinoma, and thoracic aortic aneurysms and aortic dissections." (PMID 33327285, 2020). "It seems as if patients with mutations in APC, BMPR1A, SMAD4 and GREM1 can have similar polyposis phenotypes but carriers of GREM1 mutation with HMPS might not have the same risk for extra-colonic disease as patients with BMPR1A mutations and HMPS." (PMID 27696107, 2017). "Notably, however, epithelial-specific deletion of Bmpr1a does not elicit de novo crypt formation, thereby selectively implicating the loss of stromal BMP signalling in the pathology of polyposis." (PMID 33673710, 2021). "Our ultimate goal is to enable an appropriate approach to prophylactic strategies in Polish families with polyposis, especially in those patients whose APC, MUTYH, STK11, BMPR1A, and SMAD4 gene testing showed no abnormalities." (PMID 37834005, 2023).
colon cancer (12 papers, 2004 to 2025). "A mutation of the receptor BMPR1A (bone morphogenetic protein receptor type IA) also promotes colon cancer." (PMID 25897433, 2015). "The presence of germ-line-inactivating mutations in the BMPR1A gene has been found to be responsible for a significant proportion of cases of juvenile polyposis syndrome, an inherited hamartomatous polyposis syndrome with a risk of colon cancer." (PMID 15026806, 2004). "Recently it was shown that deletion of BMPR1a in colon cancer can sensitize cells to chemotherapy, and that the constitutively active form of BMPR1a can drive chemo-resistance." (PMID 26274893, 2015). "We only observed marginally significant associations with BMP2 (PARTP = 0.083), BMPR1A (PARTP = 0.053), BMPR1B (PARTP = 0.069) for colon cancer survival." (PMID 25541970, 2014). "miRNA-885-3p could also disrupt angiogenesis through regulation of BMPR1A and repression of BMP/Smad/Id1 signaling, thereby suppressing the growth of colon cancer cell xenografts." (PMID 36064409, 2022). "Although BMPR1A was a good candidate for involvement in the pathogenesis of sporadic colon cancer, no mutations have yet been identified in primary colorectal tumours displaying LOH at the BMPR1A locus." (PMID 15026806, 2004).
prostate carcinoma (10 papers, 2012 to 2024). A carcinoma that arises from epithelial cells of the prostate gland. "The framework for diagnosis and prospective treatments in prostate cancer have already been described, which also demonstrated the increased risk of genomic loss of BMPR1a enriched in metastatic castrate resistant prostate cancer." (PMID 36054271, 2023). "Deep deletion of BMPR1A was a frequent event in prostate cancers, this has previously been shown to be related to the loss of the PTEN locus, which is associated with invasive forms of prostate cancer." (PMID 27114889, 2016). "We next wanted to examine if BMPR1a loss in myeloid cells influences prostate cancer progression." (PMID 32318332, 2020). "We found that conditional deletion of BMPR1a in myeloid cells (LysMCre) restricts tumor progression in a syngeneic mouse prostate cancer model." (PMID 32318332, 2020). "The confirmation for this declaration is provided by the fact that deactivating mutations in SMAD 4 and BMPR1A, that are members of the TGF-β superfamily and cause prostate cancer." (PMID 29719616, 2018). "In prostate cancer BMPR1A and especially BMPR2 downregulation has been correlated with disease progression and activity of BMPR2 has been shown to function in a proliferation suppressive way." (PMID 22277058, 2012). "Our findings suggest that inhibiting BMPR1a signaling may be a viable therapeutic approach for prostate cancer patients." (PMID 32318332, 2020). "As BMPR1A was proposed to convey a stimulatory effect on prostate cancer cell growth specifically, its increased expression may serve to fulfil similar roles in the progression of EBV-associated epithelial malignancies." (PMID 32708289, 2020). "Similar to these findings, a previous study reported that benign prostate specimens expressed high levels of BMPR1A; however, prostate-cancer specimens expressed much lower levels of BMPR1A, which suggests that loss of BMPR1A may play a vital role during the progression of prostate cancer." (PMID 23531103, 2013). "The mouse FVBn syngeneic prostate cancer cell line MyC-CaP was subcutaneously injected into the flank of CTL and BMPR1a cKO male mice." (PMID 32318332, 2020). "However, the finding that BMPR1b and not BMPR1a is elevated in blastic‐like prostate cancer cell lines is compelling." (PMID 36054271, 2023). "Thus, ablation of Bmpr1a and the resulting reduction in Nkx3.1 might not be sufficient to induce prostatic carcinoma." (PMID 24731097, 2014). "However, the role of Bmpr1a in prostatic cancer has not been elucidated." (PMID 24731097, 2014). "In order to test whether our identified BMPR1A-biased BMP2 expression biomarker was useful across tumour types, we investigated disease free survival in Ovarian, Lung, Pancreatic and Prostate cancers, but found no significant alterations." (PMID 27114889, 2016).
Obesity (9 papers, 2011 to 2019). Accumulation of substantial excess body fat. "It is also involved in the regulation of adipogenesis and variants of BMPR1A are associated with human obesity." (PMID 28454565, 2017). "Based on the literature, some genes are associated with obesity; for example, BMPR1A is associated with human obesity." (PMID 24339942, 2013). "Genetic variants of BMP receptor 1A gene (BMPR1A) were associated with human obesity." (PMID 31831718, 2019). "We could recently show that BMPR1A mRNA expression in both visceral and subcutaneous adipose tissue as well as genetic variants in this gene strongly correlated with obesity and its related traits." (PMID 21311592, 2011). "Because BMP-4 uses predominantly BMPR1A as its receptor, these results suggest that BMP-4/BMPR1A signaling may be involved in the pathogenesis of human obesity." (PMID 24170999, 2013). "In one study, visceral and subcutaneous BMPR1A mRNA expression levels were significantly higher in overweight and obese individuals compared with lean subjects, and BMPR1A mRNA expression correlated strongly with measures of obesity, including BMI, percentage body fat, and waist-to-hip ratio." (PMID 24170999, 2013). "Also our recent studies on BMPR1A, partner in the receptor complex with BMPR2, suggest a regulatory role of these receptors in obesity." (PMID 21311592, 2011). "For example, a signalling pathway involving BMP4 and its receptor BMPR1A influences insulin secretion and may contribute to obesity; mice lacking the HMGA2 homolog had a reduction in fat mass and were resistant to diet induced obesity." (PMID 24823714, 2014). "Consistent with recent studies on BMPR1A, positive correlation of BMPR2 mRNA expression with obesity suggests that obese individuals may have enhanced BMP-2/4 signalling, which may stimulate adipose tissue differentiation thereby contributing to increased fat mass." (PMID 21311592, 2011).
Familial adenomatous polyposis (8 papers, 2017 to 2025). Familial adenomatous polyposis (FAP) is characterized by the development of hundreds to thousands of adenomas in the rectum and colon during the second decade of life. "Four of the pathogenic or likely pathogenic variants were found in BMPR1A in patients with unexplained familial adenomatous polyposis or atypical adenomatous polyposis, which extends the genotype-phenotype spectrum for this gene." (PMID 27696107, 2017).
juvenile polyp (7 papers, 2015 to 2025). A non-neoplastic hamartomatous polyp that arises from the stomach and intestinal tract. "Analysis of patients fulfilling the clinical criteria for JPS and having pathogenic variants in BMPR1A has shown that in addition to juvenile polyps, up to half of the carriers may have other types of polyps, too, such as adenomatous or serrated polyps." (PMID 41023686, 2025). "All patients with a PV in SMAD4 or BMPR1A had polyps removed and, furthermore, in approximately 15% of the patients no juvenile polyps (but other types) had been removed." (PMID 37354305, 2023).
polyp (7 papers, 2013 to 2025). A usually exophytic mass attached to the underlying tissue by a broad base or a thin stalk. "Loss of BMPR1A in Col1a2 expressing cells resulted in major histological changes in the colon and serrated polyp development in the small intestine." (PMID 36326956, 2023). "Taken together, these data suggest that abrogation of fibroblast or myofibroblast-specific BMPR1A signaling, in contrast to endothelial BMPR1A signaling, leads to disturbed intestinal homeostasis and serrated polyp formation." (PMID 36326956, 2023). "In a European retrospective study, polyps in the small intestine were even less common in BMPR1a DCV carriers (3.2%) compared to SMAD4 DCV carriers (15.7%)." (PMID 37400896, 2023). "We show that loss of BMPR1A signaling in fibroblasts leads to polyp development through upregulation of CXCL12, driving epithelial cell proliferation and serrated polyp formation." (PMID 36326956, 2023). "The BDNF and BMPR1A expression of gallbladder adenocarcinoma, peritumoral tissues, adenoma, polyp and chronic cholecystitis were Immunohistochemically determined." (PMID 23531103, 2013). "Among 25 proven or obligatory BMPR1A variant carriers with gastrointestinal polyps or cancer from HNPCC20, individual V.2 (who was not included in our original investigation) showed a juvenile polyp in the gastric corpus at ~ 40 years of age." (PMID 41023686, 2025). "Inactivation of either of BMPR1A and SMAD4 is a crucial step in polyp development of JPS." (PMID 33327285, 2020). "When all100 gallbladder adenocarcinoma, 46 peritumoral, 30 adenoma, 15 polyp and 35 chronic cholecystitis samples were assessed, the positive rate of BDNF was inversely related to that of BMPR1A, due to the analysis of Pearson correlation coefficients (r = −7.482, P < 0.05)." (PMID 23531103, 2013).
renal fibrosis (7 papers, 2015 to 2025). A final common manifestation of a wide variety of chronic kidney diseases characterized by glomerulosclerosis and tubulointerstitial fibrosis. "Low-dose tacrolimus exerts antifibrotic, renoprotective effects in a model of renal fibrosis via ARNT-mediated transcription of bone morphogenetic protein receptor type 1A." (PMID 34424825, 2021). "Recently, Sugimoto and colleagues provided evidence of effective renal fibrosis resolution following the administration of an activator of Activin-like kinase 3 (ALK3/BMPR1A), namely THR-123." (PMID 34968236, 2020). "Among the mesenchyme morphogenesis-related genes, bone morphogenetic protein receptor type 1A (BMPR1A) and its ligand bone morphogenetic protein (BMP) play a role in renal fibrosis in chronic kidney disease." (PMID 40149644, 2025).
colorectal polyps (6 papers, 2015 to 2024). "Young age of diagnosis and high colorectal polyp numbers are not only seen in DCVs in coding regions of BMPR1a, as there was one patient with a splice site DCV at intron 4, c.430 + 2 T > C, was diagnosed at age one with > 50 colorectal polyps." (PMID 37400896, 2023).